KDF1 (keratinocyte differentiation factor 1)
Description:
Plays a role in the regulation of the epidermis formation during early development. Required both as an inhibitor of basal cell proliferation and a promoter of differentiation of basal progenitor cell progeny (By similarity).
Synonyms: C1orf172; FLJ34633; RP11-344H11.3; ECTD12
Tractability: Antibody: the Human Protein Atlas places it where antibodies can reach.
Gene: Protein-coding gene on chromosome 1 (26,949,556 to 26,960,788, reverse strand). Ensembl gene ENSG00000175707.
Subcellular location: Cytoplasm; Cell junction
Subcellular location (Human Protein Atlas): Plasma membrane; Cytosol
Gene Ontology:
Molecular function: protein binding
Biological process: developmental growth; establishment of skin barrier; limb epidermis development; morphogenesis of embryonic epithelium; negative regulation of stem cell proliferation; positive regulation of epidermal cell differentiation; regulation of epidermal cell division; keratinocyte development
Cellular component: cell junction; cytoplasm; anchoring junction; cell cortex; cell leading edge
Genetic constraint (gnomAD): Loss-of-function variants: 11 observed, 31.98 expected, observed/expected ratio (o/e) 0.34, 90% interval 0.22 to 0.57. The upper end of that interval is the gene's LOEUF score, 0.57, which puts it in group 2 of 6, group 1 being the genes least tolerant of losing a copy. Missense variants: 476 observed, 556.56 expected, observed/expected ratio (o/e) 0.86, 90% interval 0.79 to 0.92. Synonymous variants: 205 observed, 216.83 expected, observed/expected ratio (o/e) 0.95, 90% interval 0.84 to 1.06.
Gene-disease validity (ClinGen):
ClinGen rates the evidence that KDF1 causes each of these diseases.
ectodermal dysplasia 12, hypohidrotic/hair/tooth/nail type (autosomal dominant): Definitive.
Homologues: Orthologues: chimpanzee KDF1 (99% identical), macaque KDF1 (98% identical), dog KDF1 (93% identical), rabbit KDF1 (92% identical), pig KDF1 (92% identical), rat Kdf1 (92% identical), mouse Kdf1 (91% identical), guinea pig KDF1 (91% identical), tropical clawed frog kdf1 (44% identical), zebrafish kdf1a (31% identical), zebrafish kdf1b (25% identical).
Diseases named in the same sentence as KDF1 in open-access papers:
KDF1 is named in the same sentence as 17 diseases in open-access papers, as found by Europe PMC text mining. Sharing a sentence is not in itself a finding about the gene and the disease. The quoted sentences say what the papers report.
tooth agenesis (4 papers, 2020 to 2025). A tooth disease characterized by failure to develop one or more missing teeth. "Our study demonstrates for the first time that the newly recognized dental syndrome including natal teeth, tooth agenesis, and root maldevelopment is caused by a KDF1 variant." (PMID 40554824, 2025). "The family we report herein with a pathogenic variant (c.845T>G; p.Ile282Ser) in the KDF1 gene had isolated tooth agenesis, which in most cases was preceded by multiple natal teeth." (PMID 40554824, 2025). "Subsequently, other researchers segregated a novel pathogenic KDF1 variation into a non-syndromic tooth agenesis family." (PMID 36293320, 2022). "This previous genetic evidence revealed the relevance of KDF1 variations to tooth agenesis and suggested an indispensable pathogenic role of KDF1 in tooth agenesis." (PMID 36293320, 2022). "Variant analysis of 151 probands with tooth agenesis revealed a proband from family #285 carrying a novel heterozygous variation (NM_152365.3:c.920G>C; NP_689578.2:p.R307P) of KDF1." (PMID 36293320, 2022). "Among several genes involved in tooth development, mutations in MSX1, PAX9, AXIN2, WNT10A, EDA and KDF1 have been reported to play a role in tooth agenesis 6–13." (PMID 33014315, 2020). "In our study, the detection rate of the KDF1 variant was 0.66% in patients with tooth agenesis." (PMID 36293320, 2022). "Therefore, only three KDF1 variations have been reported to be associated with ectodermal dysplasia or non-syndromic tooth agenesis, and our 0.66% variation detection rate further substantiated the rarity of KDF1 variations that contribute to tooth agenesis." (PMID 36293320, 2022). "Here, we employed whole-exome sequencing (WES) and Sanger sequencing to screen for the suspected variants in a cohort of 151 tooth agenesis patients, and we segregated a novel KDF1 heterozygous missense variation, c.920G>C (p.R307P), in a non-syndromic tooth agenesis family." (PMID 36293320, 2022). "In particular, mutation of KDF1 has been reported to be associated with tooth agenesis." (PMID 34136411, 2021). "In this study, we identified a previously undescribed KDF1 heterozygous missense variation in one non-syndromic tooth agenesis family using whole-exome sequencing (WES) and Sanger sequencing." (PMID 36293320, 2022). "Our findings indicated that KDF1 variation c.920G>C;p.R307P was inherited in an autosomal-dominant manner in this non-syndromic tooth agenesis family." (PMID 36293320, 2022). "In this study, we identified the previously undescribed KDF1 heterozygous missense variation c.920G>C;p.R307P in two individuals segregated from one non-syndromic tooth agenesis family." (PMID 36293320, 2022). "Our study elaborated on the tooth abnormalities that occur with KDF1-related tooth agenesis and identified, for the first time, oral epithelium defects associated with KDF1-related tooth agenesis." (PMID 36293320, 2022). "Our study identified a novel heterozygous KDF1 variation (c.920G>C;p.R307P) in an autosomal-dominant inherited non-syndromic tooth agenesis family." (PMID 36293320, 2022). "Our results from Wnt luciferase assessments demonstrated that the novel KDF1 R307P variant and the other three reported variants suppressed Wnt signaling activation, suggesting that the loss-of-function of the variant allele might be the pathogenic mechanism of KDF1 variation in tooth agenesis." (PMID 36293320, 2022). "Mutations of several genes such as PAX9, MSX1, AXIN2, KDF1 and WNT10A have been reported which are associated with non-syndromic tooth agenesis." (PMID 33014315, 2020). "However, the genetic mechanisms of KDF1 variations in tooth agenesis cases are still unclear." (PMID 36293320, 2022). "Keratinocyte differentiation factor 1 (KDF1; OMIM *616758) is the most recently identified, rare candidate gene for tooth agenesis." (PMID 36293320, 2022).
ovarian carcinoma (3 papers, 2022 to 2024). A malignant neoplasm originating from the surface ovarian epithelium. "After removing clinical confounding factors by multivariate Cox regression, the results showed that KDF1 (p = 0.04), platinum resistance (p < 0.001), and initial treatment outcome (p < 0.001) were independent risk factors for the prognosis of ovarian cancer." (PMID 35281796, 2022). "After analysis combining the relevant clinical features, we found that the high expression of KDF1 is an independent prognostic factor of ovarian cancer and associated with platinum resistance and tumor metastasis in ovarian cancer." (PMID 35281796, 2022). "All studies indicated that KDF1 can be a potential diagnostic marker and therapeutic target for ovarian cancer." (PMID 35281796, 2022). "The forest plot drawn according to Cox multivariate regression after incorporating relevant clinical features suggests that the high expression of KDF1, platinum resistance, and primary therapy outcome are risk factors for low OS in patients with ovarian cancer." (PMID 35281796, 2022). "In ovarian cancer, KDF1 was reported to play an oncogenic role, while it served as a tumor suppressor in renal cell carcinoma." (PMID 39171503, 2024). "Univariate Cox regression suggested that stage (p = 0.05), platinum resistance (p < 0.001), and primary treatment outcome (p < 0.001) were related to the prognosis of ovarian cancer, and KDF1 had a trend to reach statistical significance (p = 0.07)." (PMID 35281796, 2022). "Then we further validated that the high expression of KDF1 had a close correlation with the stage and grade of ovarian cancer in ovarian cancer tissue chips." (PMID 35281796, 2022). "We found that KDF1 participated in the Wnt/β-catenin pathway in ovarian cancer by empirical research." (PMID 35281796, 2022). "We first detected the location and expression of KDF1 in ovarian cancer tissues using immunochemistry." (PMID 35281796, 2022). "Relationship between clinicopathologic parameters and expression of KDF1 in 110 cases of ovarian cancer." (PMID 35281796, 2022). "A recent study demonstrated that KDF1 can activate the Wnt signaling pathway to regulate the epithelial-to-mesenchymal transition process in ovarian cancer." (PMID 36293320, 2022). "In our study, we combined bioinformatics research and in vivo and in vitro study to systematically prove that KDF1 was a potential oncogene of ovarian cancer." (PMID 35281796, 2022). "Bioinformatics research led us to see the strong potential of KDF1 in the occurrence, progression, and prognosis of ovarian cancer, and guided our mechanism research direction into the next stage." (PMID 35281796, 2022). "To investigate the function of KDF1 in ovarian cancer, we screened the mRNA expression of KDF1 in ovarian cancer cell lines." (PMID 35281796, 2022). "Then, we confirmed that KDF1 is highly expressed in ovarian cancer tissues in the immunohistochemistry assay." (PMID 35281796, 2022). "Then the expression of KDF1 in ovarian cancer tissues was validated by streptavidin–peroxidase (SP) immunohistochemistry." (PMID 35281796, 2022). "Our study confirmed that the expression of KDF1 can regulate the phenotype and function of ovarian cancer cells." (PMID 35281796, 2022). "It was found that the difference of the OS–KM curve and the PFS–KM curve of ovarian cancer patients between the KDF1 high- and low-expression groups was statistically significant (p = 0.028) (p = 0.0024)." (PMID 35281796, 2022). "Although studies have shown that KDF1 is associated with tumor-related molecules, so far, the expression and function of KDF1 in epithelial ovarian cancer have not been reported." (PMID 35281796, 2022). "The expression of KDF1 in ovarian cancer was relative to grade and stage." (PMID 35281796, 2022).
ovarian carcinoma (continued). "Therefore, in this research, we combined bioinformatics and experimental study to investigate the expression pattern and function of KDF1 in epithelial ovarian cancer and explore the value of KDF1 in EOC diagnosis and treatment." (PMID 35281796, 2022). "The present study investigated the function and the potential mechanism of KDF1 in ovarian cancer." (PMID 35281796, 2022). "The expression of KDF1 was higher in ovarian cancer tissues than that of normal ovarian tissues." (PMID 35281796, 2022). "However, the role of KDF1 has not been reported in ovarian cancer." (PMID 35281796, 2022).
breast carcinoma (1 paper, 2022). "The enrichment of the GSEA gene revealed that high expression of KDF1 was related to the EMT process of breast cancer and was negatively correlated with the cell apical junction process." (PMID 35281796, 2022).
gastric cancer (1 paper, 2024). A primary or metastatic malignant neoplasm involving the stomach. "Cell viability was reduced with the knockout of KDF1 and CDK1, supporting their role as oncogenes and potential involvement in promoting gastric cancer progression." (PMID 39171503, 2024).
hypohidrosis (1 paper, 2022). diminished sweating in response to appropriate stimuli. "A heterozygous variation in KDF1 was first reported to cause autosomal dominant syndromic tooth agenesis, namely, ectodermal dysplasia-12 (ECTD12; OMIM #617337), which manifests as congenital absent teeth, dystrophic toenails, hypohidrosis, and hair abnormalities." (PMID 36293320, 2022).
lung adenocarcinoma (1 paper, 2023). A carcinoma that arises from the lung and is characterized by the presence of malignant glandular epithelial cells. "To explore the possible role and underlying mechanism of KDF1 in lung adenocarcinoma (LUAD), we investigated KDF1 expression in LUAD tissues and the influence of KDF1 in the phenotype of LUAD cells (A549 and PC-9) as well as the underlying mechanism." (PMID 38137415, 2023).
lung carcinoma (1 paper, 2023). "Given the critical roles of p38, ERK, AKT and STAT3 pathways in lung cancer’s initiation and progression, we further examined the influence of KDF1 overexpression in these pathways." (PMID 38137415, 2023).
renal carcinoma (1 paper, 2021). A carcinoma arising from the epithelium of the renal parenchyma or the renal pelvis. "No study has reported the expression and function of KDF1 in renal cancer." (PMID 34136411, 2021).
cancer (8 papers, 2019 to 2024). A tumor composed of atypical neoplastic, often pleomorphic cells that invade other tissues. "Reduced KDF1 expression has been discovered in cancer cells, and it has been demonstrated to correlate with patient survival positively and negatively correlate with tumor grade." (PMID 38742936, 2024). "For tissue homeostasis and cancer prevention, KDF1 plays a crucial function in preserving the right balance between cell division and differentiation." (PMID 38742936, 2024). "The enhanced KDF1 in the tumor tissues was observed in the cancer cells (shown by a black arrow) as well as in some non-cancer cells (shown by a blue arrow)." (PMID 38137415, 2023). "We observed that the expression level of p-STAT3 is positively correlated with the level of KDF1 in the cancers (r = 0.458, p < 0.01)." (PMID 38137415, 2023). "Compared with the paired adjacent alveolar epithelial cells, in most cases, the cancer cells expressed a much higher level of KDF1." (PMID 38137415, 2023). "Of note, although not reaching the statistical significance level (p = 0.065), the cancer cells in the advanced-stage group tended to have increased KDF1 compared to the early-stage group." (PMID 38137415, 2023). "Cancer cells of the large tumor group were found to harbor a higher KDF1 expression level compared to the smaller tumor group." (PMID 38137415, 2023). "KDF1 was upregulated in the cancer cells of LUAD patients and significantly correlated with tumor size and OS." (PMID 38137415, 2023). "We observed an obvious positive association between the expression level of KDF1 and that of p-STAT3: LUAD cancer cells expressing a high level of KDF1 usually express a high level of p-STAT3 and vice versa." (PMID 38137415, 2023). "Elevated levels of AATK1, RFN144A, βArr1, and βArr2 KDF1 gene expression lead to various cancer cell inhibitions." (PMID 37958599, 2023). "Patients with elevated KDF1 levels in cancer cells (compared with paired alveolar epithelial cells) had shorter OS than those without elevated KDF1 levels in cancer cells." (PMID 38137415, 2023). "Patients of ccRCC with higher KDF1 protein in cancer cells were found to have longer OS and DSS and KDF1 was demonstrated to be an independent factor associated with patients’ DSS." (PMID 34136411, 2021). "KDF1 was found to be decreasingly expressed in the cancer cells and correlated negatively with the tumor grade and positively the survival of the patients." (PMID 34136411, 2021). "It was upregulated in 12 cancers and downregulated in 10 cancers, indicating that KDF1 might be extensively involved in the pathogenesis and carcinogenesis." (PMID 38137415, 2023). "Indeed, as shown in this study, the expression of KDF1 was found to be dysregulated in most of the cancers analyzed." (PMID 38137415, 2023). "KDF1 was observed to be differentially expressed in 22 out of the 26 types of cancers analyzed." (PMID 38137415, 2023). "The function of KDF1 revealed in regulation of cell differentiation and proliferation suggests that it may also have roles in the pathogenesis of cancers, a group of diseases that occur due to uncontrolled proliferation." (PMID 38137415, 2023). "The present finding that KDF1 may participate in the process of LUAD pathogenesis has provided us with new evidence for the involvement of this molecule in cancers." (PMID 38137415, 2023). "It is suggested that KDF1 and cancer progression, especially through the interaction with E-cadherin, may participate in the Wnt/β-catenin pathway and regulate the EMT process, promoting the proliferation and invasion of OV." (PMID 35281796, 2022). "Research showed that KDF1 was decreasingly expressed in the cancer cells and correlated negatively with the tumor grade and positively with the survival of the patients, which means KDF1 may function as a tumor suppressor." (PMID 35774505, 2022). "Immunostaining for KDF1 was observed mainly in the cytoplasm of cancer cells." (PMID 34136411, 2021).
cancer (continued). "To determine whether this was also the case in the cancer cells of LUAD tumor tissues, we further examined p-STAT3 expression in the cancer cells of LUAD tumor tissue samples and associated them with the expression level of KDF1." (PMID 38137415, 2023). "However, data about the involvement of KDF1 in cancers are still limited." (PMID 38137415, 2023). "Given the key role of KDF1 in the maintenance of the appropriate balance between cell division and differentiation, which is critical for tissue homeostasis and cancer prevention, we speculated that defect in KDF1 might also play a role in the pathogenesis of cancer." (PMID 34136411, 2021). "In our study, higher levels of CDK1 and KDF1 expression in noncancerous gastric mucosa were associated with an increased risk of future cancer development, suggesting that elevated expression of these markers may indicate a precancerous condition and play a role in gastric tumorigenesis." (PMID 39171503, 2024). "Finally, in the cancer cells of LUAD tumor samples, the KDF1 level was observed to correlate positively with the level of p-STAT3." (PMID 38137415, 2023). "Patients with enhanced KDF1 in cancer cells (compared with paired adjacent non-neoplastic lung epithelial cells) had shorter overall survival than patients with no increased KDF1 in cancer cells." (PMID 38137415, 2023). "Among the 147 cases that have both tumor tissue and adjacent non-tumor lung tissue, 108 cases were found to have obviously higher immunostaining for KDF1 in the cancer cells than in the paired adjacent non-tumor epithelial cells." (PMID 38137415, 2023). "Compared to non-tumor lung epithelial cells, KDF1 was upregulated in the cancer cells of the majority of LUAD patients, and its expression was correlated with tumor size." (PMID 38137415, 2023). "KDF1 was upregulated in LUAD tissues and might contribute to the progression of LUAD by enhancing the proliferation, migration and invasion of LUAD cancer cells via activation of the STAT3 pathway and AKT pathway." (PMID 38137415, 2023). "The level of KDF1 protein in the cancer cells was found to correlate negatively with tumor grade." (PMID 34136411, 2021). "This suggests that KDF1 and CDK1 may be markers independent of intestinal metaplasia severity, and could play a distinct role in MGC progression apart from the gastric precancerous cascade, potentially being more linked to cancer development rather than premalignant changes." (PMID 39171503, 2024).